USP7 (ubiquitin specific peptidase 7)
Diseases named in the same sentence as USP7 in open-access papers (continued):
Sharing a sentence is not in itself a finding about the gene and the disease.
cancer (continued). "However, it should be considered that in other cancer types USP7 over-expression has been commonly correlated with both disease progression and advanced stages, therefore suggesting that USP7 over-expression in CLL may play a pathogenetic role even in the early stages of this disease." (PMID 28418900, 2017). "USPs, such as USP1, USP2, USP7, USP9x and USP14, were recently shown to contribute to the development of cancer and are emerging as novel cancer drug targets." (PMID 27780924, 2016). "Several members of the DUB family are known to contribute to carcinogenesis, including USP1, USP2, USP7 and USP22, while other DUBs are down-regulated in human cancers, including USP10 and BAP1." (PMID 27030989, 2016). "The deubiquitylation enzyme USP7/HAUSP plays a major role in regulating genome stability and cancer prevention by controlling the key proteins involved in the DNA damage response." (PMID 22361354, 2012). "Proteomic and cellular analyses reveal that selective USP7 degradation modulates both shared and distinct protein sets across both cancers without affecting cell growth." (PMID 42129197, 2026). "Furthermore, the MYC, DDX21, USP7, RFC4, APEX1, CDK9, and NOP2 of the “cancer cells_vs_all-PDAC” group play a critical role in the metabolic reprogramming of the PDAC, contributing to the poor prognosis of PDAC." (PMID 40906153, 2025). "Of particular interest, this study demonstrated that inhibition of USP7 could sensitise HPV- HNSCC cells to both radiation treatment and PARP inhibition, suggesting that combination therapies may be beneficial in these cancers." (PMID 40011575, 2025). "Furthermore, docking studies revealed that acetylated compounds exhibited a stronger affinity for HER2 than for USP7, suggesting HER2 as the likely receptor target, given its presence alongside USP7 in the A2780 cancer cell line." (PMID 40142049, 2025). "However, as another study demonstrated that USP7 levels are decreased in HPV + HNSCC, the clinical utility of USP7 inhibitors in these cancers is unclear and requires further investigation." (PMID 40011575, 2025). "Moreover, mTOR inhibitors enhanced YCH2823 efficacy, highlighting a promising therapeutic strategy to extend the clinical utility of USP7 inhibitors, particularly in MYCN-amplified cancers." (PMID 41157055, 2025). "Again, USP7 inhibition did not impact cell migration in either cancer cells, fibroblasts or endothelial cells." (PMID 38602256, 2024). "For example, since 2015, several DUBs-targeted agents, including VLX1570 (targeting USP14), P22077 (targeting USP7/USP10/USP47), P5091 (targeting USP7/USP47), and spautin-1 (targeting USP10/USP13), have been investigated in the clinic to treat certain types of cancers." (PMID 39522000, 2024). "Regardless of the method of stimulation, treatment with USP7 inhibitor led to a significant decrease in VEGF secretion from activated fibroblasts and cancer‐associated fibroblasts." (PMID 38602256, 2024). "USP7 has been proposed to deubiquitinate and stabilise HIF-1α in several cancer line cell types." (PMID 39584532, 2024). "This represents a function of USP7 that is unique to fibroblasts, and which is not observed in cancer cells or other components of the TME." (PMID 38602256, 2024). "The role of USP7 in various types of cancer is well-established; however, its role in NDDs has not been elucidated to date." (PMID 37874827, 2023).
cancer (continued). "Surprisingly, the in vivo experiment data showed that USP7 inhibitor treatment only slightly suppressed the parental A549 cancer xenograft growth, which was not consistent with the in vitro cell culture data." (PMID 37946202, 2023). "USP7 is a deubiquitinating enzyme (DUB) that can alter the degradation rate and cellular localization of specific protein substrates, some of which are of high interest in cancer progression." (PMID 37582753, 2023). "Taken together, our findings demonstrate that USP7 inhibition can dramatically upregulate USP22 in cancer cells; and targeting USP7 and USP22 may represent a more effective approach for targeted cancer therapy, which warrants further study." (PMID 37946202, 2023). "Therefore, like USP7, accumulating evidence indicates that USP22 also represents a promising target for cancer therapy, and USP22 knockdown markedly decreases cancer growth, induces apoptosis, and sensitizes cancer cells to chemo-radio and immune therapies." (PMID 37946202, 2023). "Protein stability analysis demonstrated that FT671 significantly promoted the degradation of both SP1 and β-Catenin in A549 cancer cells, indicating this may be one of the mechanisms for decreased SP1 by USP7 inhibition." (PMID 37946202, 2023). "Therefore, we conducted a comparative analysis to assess the impact of co-depletion of USP7 and USP47 versus individual depletion on cancer cell growth." (PMID 37740002, 2023). "The findings of our study have strongly suggested that targeting both USP7 and USP22 may represent a novel, more effective therapeutic approach for cancer treatment, which warrants further study." (PMID 37946202, 2023). "Consistent with our previous observation in cancer cell lines and organoids, deletion of Usp7 in the Apc WT animals does not perturb intestinal homeostasis." (PMID 36669491, 2023). "The combination of USP7 inhibition with anti-MDM2 therapy and PD-1 blockade may appear highly effective in enhancing cancer immunotherapy." (PMID 36428632, 2022). "USP4, USP7, and USP47 are DUBs that are abnormally overexpressed in many cancers." (PMID 35884836, 2022). "Compared with other DUBs, such as BAP1 and USP7, OTUD3 is rarely studied in cancer." (PMID 34380780, 2021).
cancer (continued). "Moreover, USP7 impacts mainly on the nuclear activities of PTEN and FOXO, which were forced to the nucleus by USP7 inhibition and sufficient to induce cancer cells apoptosis." (PMID 32002017, 2020). "Importantly, cisplatin and paclitaxel promote miR-522 secretion from CAFs by activating USP7/hnRNPA1 axis, leading to ALOX15 suppression and decreased lipid-ROS accumulation in cancer cells, and ultimately result in decreased chemo-sensitivity." (PMID 32106859, 2020). "Thus far, very little is known about USP47 in cancer, even though USP47 has high sequence similarity with USP7 of whose inhibitors are now actively developed as an anticancer drug." (PMID 32370049, 2020). "Collectively, our findings suggest thatcombined treatment with a USP7 inhibitor and an EZH2 inhibitor may be a rationalstrategy for the treatment of EZH2-dependent cancers." (PMID 32453339, 2020). "Our findings suggest that USP7 and FBXO38 may both be useful targets for inhibiting the growth of cancer cells with KIF20B overexpression." (PMID 30804394, 2019). "USP7, also known as HAUSP, plays an oncogenic role in the process of cancer development." (PMID 30319415, 2018). "Considering that USP7 is upregulated in many cancers, this might be one of the possible reason for high levels of UHRF1 in cancer cells." (PMID 28881702, 2017). "Furthermore, several DUBs, including HAUSP/USP7, USP10, USP11, USP13, OTUD3, and Ataxin-3 have been shown to reverse the ubiquitination of PTEN, a key antagonist in the PI3K growth-promoting pathway, implicating its function in cancer-specific contexts." (PMID 39075050, 2024). "On the other hand, several ubiquitin-specific peptidases, including USP7, USP22, OTUB1, and CSN5, regulate PD-L1 protein expression in an opposing fashion through removal of the polyubiquitin modification from PD-L1 and consequently protect PD-L1 from proteasomal degradation in cancer cells." (PMID 38038129, 2023).
cancer (continued). "Thus, we propose opposing regulatory mechanisms of DLC1 protein homeostasis by USP7 and HECTD1, which could open up strategies to counteract downregulation and restore DLC1 expression in cancer." (PMID 35322810, 2022). "Besides OTUB1, other DUBs, such as USPs family (USP1, USP7, USP8, USP15, USP22), OTUs family (OTUD7B, OTUD6B, A20, and OTUB2) and other DUBs have been identified to regulate the progression of various cancers and applied for clinical cancer therapy." (PMID 35715413, 2022). "Based on our findings that USP7 deubiquitinated H2BK120ub1 and recruited the PRC2 complex to suppress the transcription of FOXO1, we postulated that the tumorigenic effect of USP7/EZH2-FOXO1 signaling pathway could be extended to a broader scope of cancers." (PMID 33849069, 2021). "Thus, we suggest thatsimultaneous treatment with a USP7 inhibitor and an EZH2 inhibitor could be arational strategy for treating EZH2-dependent cancers." (PMID 32453339, 2020). "Therefore, in thefuture, it may be possible to combine these drugs or apply them sequentiallydepending on the expression patterns of USP7, CCDC6, and EZH2 in individual cases ofprostate cancer to provide novel forms of customized therapy." (PMID 32453339, 2020). "Since USP7 was first discovered as a herpesviral interacting protein by Meredith and colleagues, numerous studies have contributed to our knowledge about this deubiquitinating enzyme (DUB) and defined its important role in not only herpesviral diseases but also cancer-related processes." (PMID 23555268, 2013). "However, to the best of our knowledge, no targeted agents against UBE2T, UBE2C, BIRC5, or USP9X, either approved or in development, can be found in The Drug Gene Interaction Database or Genomics of Drug Sensitivity in Cancer database, while the only USP7 inhibitor, P22077, has not been tested in BC." (PMID 33671201, 2021). "Moreover, the carcinogenic role of USP7 in these types of cancer has been attributed to USP7-mediated deubiquitination and stabilization of MDM2 and MDMX, which has been validated by demonstrating the anticancer activity of USP7 inhibitors in vitro and in vivo." (PMID 32300595, 2020). "Therefore, we suggest that the clinical usage of USP7 inhibitors, by downregulating the CCDC6 levels, might increase the sensitization to olaparib and enhance the response to standard chemotherapeutics in combined therapy in cancer cells." (PMID 25885523, 2015). "Therefore, further research on the ubiquitination sites of Raf-1 regulated by E3 ligases or USP7 is expected to modulate the ERK1/2 signaling pathway by selectively regulating the stability or activity of Raf-1, which could be a new therapeutic strategy in the ERK1/2 cascade activated cancers." (PMID 35948545, 2022). "Previous studies using cancer cell lines HCT116 and U2OS showed that knocking down USP7 did not change Tip60 mRNA levels." (PMID 29236775, 2017).
cancer (continued). "Collectively, these results illustrate the non-redundancy of USP47 compared to USP7 by showing that co-depletion of USP7 and USP47 using siRNA co-transfection results in a more significant reduction of cancer cell growth compared to depleting each independently." (PMID 37740002, 2023). "Therefore, we speculated that USP7 inhibition may promote PTEN reactivation and consequently cancer selective apoptotic induction, without affecting normal cells." (PMID 28418900, 2017).
tumor (255 papers, 2011 to 2026). "Mechanistically, the levels of fructose-2,6-bisphosphate (F-2,6-BP) are decreased in tumor cells upon glucose deficiency, which enhances the interaction between ubiquitin carboxyl-terminal hydrolase 7 (USP7) and PFKM." (PMID 41818193, 2026). "Inhibition of USP7 caused DNA damage in chronic lymphocytic leukemia cells, leading to tumor cell death." (PMID 40006058, 2025). "USP7 expression in HCC tissues is significantly higher than in the surrounding non-tumor tissues, and it is associated with shorter overall survival and a higher cumulative recurrence rate of HCC47-49." (PMID 40607251, 2025). "USP7 is a deubiquitinase previously reported to regulate inflammatory signaling pathways within tumor-associated microenvironments." (PMID 40947005, 2025). "In the tumor microenvironment, USP7 plays a significant role in the reprogramming of tumor-associated macrophages (TAMs)." (PMID 39767641, 2024). "A recent study showed that high USP7 expression was associated with poor survival and later tumor stage in GBM." (PMID 38254206, 2024). "In this context, USP7 promotes the function of regulatory T cells, regulates polarization of tumor-associated macrophages, and the expression of programmed death-ligand 1 (PD-L1) in tumor cells." (PMID 39430244, 2024). "Ubiquitin-specific protease 7 (USP7, also known as HAUSP) is frequently overexpressed in various tumors, including breast, prostate, colorectal, and lung, demonstrating that USP7 is closely associated with tumor development and progression." (PMID 38474017, 2024). "Clinically, USP7 overexpression is associated with more aggressive tumor characteristics, such as larger size, poor differentiation, elevated alpha‐fetoprotein levels, and microvascular invasion, reinforcing its key role in HCC malignancy." (PMID 39678489, 2024). "USP7 is frequently overexpressed in NB cell lines and patient tumors and has been associated with aggressive tumor behavior and poor clinical outcomes, further suggesting that USP7 inhibitors are likely to be effective against NB cells and tumors." (PMID 37762082, 2023). "Ubiquitin-specific protease 7 (USP7) is a deubiquitinase that plays a critical role in tumor suppression and DNA repair, and USP7 overexpression has been associated with tumor aggressiveness in a variety of tumors, including NB." (PMID 37762082, 2023). "Loss of Usp7 significantly reduces tumor numbers and tumor grade in both models, indicating that Apc-deficient tumor development and progression is Usp7 dependent." (PMID 36669491, 2023). "In conclusion, our data provide robust in vivo evidence of USP7 as a tumor-specific therapeutic target in APC-mutated CRCs." (PMID 36669491, 2023). "This is consistent with our earlier observation that loss of Usp7 inhibits Apc-deficient tumor development." (PMID 36669491, 2023). "We have recently identified USP7 as a tumor-specific target in CRC carrying APC-truncating mutations." (PMID 36669491, 2023). "To determine the associations of USP7 expression with NB patient outcomes and prognostic features, we used NB patient tumor gene expression data from the R2 Genomics Analysis and Visualization Platform." (PMID 37762082, 2023). "USP7 inhibition was shown to induce tumor cell death caused by the accumulation of DNA damage in chronic lymphocytic leukemia (CLL)." (PMID 36428632, 2022). "USP7 inhibition can induce the polarization of tumor-associated macrophages from M2 into M1 by activating the P38 MAPK pathway and upregulating the expression of programmed cell death 1 ligand 1 (PD-L1) in the tumor microenvironment." (PMID 35414786, 2022).